TNF (tumor necrosis factor)
Diseases named in the same sentence as TNF in open-access papers (continued):
Sharing a sentence is not in itself a finding about the gene and the disease.
chronic liver failure (10 papers, 2013 to 2022). Liver failure that develops slowly and gradually for some time, possibly for years, often as the result of cirrhosis, or malnutrition. "Odeh proposes that TNF-α plays a central role in the pathogenesis of HE associated with both acute and chronic liver failure." (PMID 27445694, 2016). "These clinical observations serve as a form of validation, as TIII may lie between TNFα levels of healthy individuals and those at-risk individuals with more severe complications (e.g., chronic liver failure)." (PMID 32868834, 2020). "In previous research, it was shown that EZH2-catalyzed H3K27 trimethylation plays a key role in acute-on-chronic liver failure via a TNF-mediated pathway." (PMID 33262329, 2020). "GSK126 has been shown to ameliorate disease severity in acute-on-chronic liver failure by modulating TNF and overall inflammation." (PMID 33262329, 2020). "Circulating levels of TNF-α are not only increased in patients with chronic liver failure but also correlate significantly with the severity of HE." (PMID 27445694, 2016). "Inflammatory molecules, including cytokines interleukin-1 (IL-1), interleukin-6 (IL-6), and tumor necrosis factor-alpha (TNF-α), are increased in plasma during acute and chronic liver failure in patients and in animals with experimentally induced HE." (PMID 23762040, 2013). "Importantly, hepatic encephalopathy patients with chronic liver failure display increased level of circulating TNF-α, and TNF-α and ammonia show a positive correlation in the patients with hepatic encephalopathy." (PMID 35464767, 2022). "Animal studies also show increased TNF-α levels in acute and chronic liver failure." (PMID 27445694, 2016). "Levels of TNF-α were found significantly higher in acute on chronic liver failure patients, especially in non-survivors." (PMID 30555804, 2018).
cocaine addiction (10 papers, 2015 to 2025). "A dedicated section focuses on key neuroimmune signaling pathways—particularly the TNF-α/NF-κB axis—and their involvement in stress-induced vulnerability to cocaine addiction." (PMID 41516262, 2025). "The results showed that non-key genes were mainly enriched in the cocaine addiction pathway, amphetamine addiction pathway, MAPK signaling pathway, TNF signaling pathway, and synaptic vesicle circulation pathway, all of which were related to cocaine addiction." (PMID 37469839, 2023). "On one hand, elucidating the mechanistic role of TLR4, IL-1β and TNF-α in cocaine-induced behavior is essential to ameliorate the understanding of progression and maintenance of cocaine addiction." (PMID 34349653, 2021). "The plasma concentrations of interleukin 1-beta (IL-1β), IL-6, IL-10, and tumor necrosis factor-alpha (TNFα) were affected by history of cocaine addiction and sex." (PMID 25762940, 2015). "KEGG results revealed that the signaling pathways mainly enriched were as follows: transcriptional misregulation in cancer, spliceosome, IL-17 signaling pathway, amphetamine addiction, TNF signaling pathway, complement and coagulation cascades, cocaine addiction, and bile secretion." (PMID 37771430, 2023). "KEGG results implied that the signaling pathways that were mainly enriched included transcriptional misregulation in cancer, spliceosome, IL-17 signaling pathway, amphetamine addiction, TNF signaling pathway, complement and coagulation cascades, cocaine addiction, and bile secretion." (PMID 37771430, 2023). "Given that TNF can modulate AMPAR content in the striatum, it became an interesting possibility that TNF could be playing a role in circuit dynamics in a model of cocaine addiction." (PMID 33192311, 2020). "Finally, the statistical analysis of TNFα concentrations revealed a significant main effect of history of cocaine addiction (F1,122 = 34.98, p < 0.001) and sex (F1,122 = 20.90, p < 0.001) after adjusting for covariates." (PMID 25762940, 2015).
disseminated candidiasis (10 papers, 2006 to 2022). Systemic candidiasis occurs when Candida yeast enters the bloodstream and may spread (becoming disseminated candidiasis) to other organs, including the central nervous system, kidneys, liver, bones, muscles, joints, spleen, or eyes. "Since TNFα is required for protection against disseminated candidiasis, further studies should focus on Klk gene expression in the kidney of TNFα-deficient mice." (PMID 27814401, 2016). "More recently, the administration of either a monoclonal anti-TNF antibody or a soluble TNF receptor increased mice susceptibility to hematogeneously disseminated candidiasis whereas only the monoclonal antibody increased susceptibility to oropharyngeal candidiasis." (PMID 28446778, 2017). "The reduced virulence of the ISW2 null mutant DRL6 in a mouse model of disseminated candidiasis was associated at day 2 PI with decreased up-regulation of IL-6, TNF-α, MIP1-α, and IL-10, cytokines and chemokines that are known to play a role in innate host defense against Candida in vivo." (PMID 27727302, 2016). "An involvement of defective TNF production in the increased susceptibility of hIL-37Tg mice to disseminated candidiasis is also consistent with earlier studies showing that mice lacking TNF or the TNF receptor are highly susceptible to disseminated candidiasis." (PMID 25620965, 2014). "Since in models of live infection blocking inflammation mediated by cytokines such as IL-1 or TNFα can be either detrimental or beneficial for the outcome of the host, we therefore carried-out studies of disseminated candidiasis in mice expressing human IL-37." (PMID 25620965, 2014). "Macrophage activation induces releasing of several key mediators, including proinflammatory cytokines such as TNF-α, which are important for protecting the host against disseminated candidiasis." (PMID 21824396, 2011). "Both TNFα and IL-6 have been shown to be protective in the mouse model of disseminated candidiasis, suggesting that unmasking β-glucan could provoke a proinflammatory response and attenuate virulence in disseminated disease." (PMID 16652171, 2006). "TNFα, a pro-inflammatory cytokine is a key mediator in protecting against disseminated candidiasis, as demonstrated by the fact that the lack of TNFα worsens the course of disseminated candidiasis." (PMID 22114559, 2011). "Lack of TLR4 and TLR2 responses were shown to affect disseminated candidiasis in mice: lack of TLR4 caused an increased C. albicans kidney burden, while blocking of TLR2 inhibited the production of inflammatory cytokines such as tumor necrosis factor alpha (TNF-α) and IL-1β." (PMID 33526565, 2021).
Down syndrome (10 papers, 2010 to 2025). "The biomarkers most frequently analyzed in studies of Down syndrome were IL-10, TNF-alpha, IL-1 beta, IL-4, IFN-gamma, and the genes STAT1, STAT3, and SOCS3, all of which are involved in the regulation of the immune response and periodontal inflammation." (PMID 41462866, 2025). "The obtained phenotypic results correlated with the molecular data and showed that Down syndrome endothelial cells exhibit decreased proliferation, reduced migration, and a weak TNF-α inflammatory response." (PMID 32934781, 2020). "The levels of IFNγ, TNFα, IL-10 in the Down syndrome group (DS) were higher than in the intellectual Disabilities (ID) group (p < 0.05)." (PMID 21496308, 2011). "Increased levels of TNF and IFN-γ message have been associated with increased thymocyte deletion and cortical depletion observed in the thymi of patients with Down-Syndrome (DS)." (PMID 21124839, 2010). "Interestingly, Down syndrome cases with preclinical AD show significant links among augmented levels of plasma TNF-α, Aβ accumulation, and the following cognitive deterioration in the subsequent years." (PMID 32296418, 2020).
erectile dysfunction (10 papers, 2015 to 2025). Persistent or recurrent inability to achieve or to maintain an erection during sexual activity. "Blockade of TNF-α action may theoretically represent an alternative therapeutic approach for erectile dysfunction, especially in pathological conditions associated with increased levels of this cytokine." (PMID 25615941, 2015). "In patients with erectile dysfunction, TNF-α levels in serum are increased; TNF-α levels are inversely related to sexual performance." (PMID 31814838, 2019). "Testicular TNF-α suppresses testosterone release, which in turn results in the erectile dysfunction (ED) seen in hyperPRL." (PMID 28763467, 2017). "Therefore, the use of anti-TNF medications could help with improving erectile dysfunction." (PMID 33449229, 2021).
esophageal squamous cell carcinoma (10 papers, 2013 to 2023). Esophageal squamous cell carcinoma (ESCC) is a type of esophageal carcinoma (EC) that can affect any part of the esophagus, but is usually located in the upper or middle third. "T. forsythia can induce pro-inflammatory cytokines such as IL-1β and IL-6 by CD4 + T helper cells and TNF-α in esophageal squamous cell carcinoma (ESCC)." (PMID 35847109, 2022). "Single nucleotide polymorphisms in TNF-α, NF-κB and its inhibitor IκB genes were shown to be associated with susceptibility and prognosis of several cancers; however, their role in esophageal squamous cell carcinoma (ESCC) is not well recognised." (PMID 24324738, 2013). "However it is found that FLOT1 can activate tumor necrosis factor-alpha (TNF-α) receptor signaling and sustain activation of NF-kappa B in esophageal squamous cell carcinoma cells." (PMID 27898717, 2016).
hypercortisolemia (10 papers, 2009 to 2026). "We found decreased concentration of TNF-α and hypercortisolemia in depressed patients." (PMID 28738849, 2017). "Hypercortisolemia with involvement of decreased concentration of TNF-α might play a significant role in suppression of IgG response in depressed patients." (PMID 28738849, 2017). "Hypercortisolemia, which we observed in our research in the patients’ group, could significantly influence TNF-α concentration." (PMID 28738849, 2017). "Concerning pro‐inflammatory cytokines such as TNF‐α, some studies propose that they may influence hippocampal atrophy by inducing systemic hypercortisolemia; other research suggests that they can directly impact neuronal death by degrading the blood–brain barrier." (PMID 39236111, 2024). "Proinflammatory cytokines (IL-1, IL-6, TNF-α) in chronic disease may cause HPA axis hyperactivity by disturbing the negative feedback inhibition of circulating cortisol, which creates a condition of hypercortisolemia." (PMID 37916198, 2023).
ischemic cardiomyopathy (10 papers, 2008 to 2025). Ischemic cardiomyopathy is a cardiomyopathy in which a weakness in the muscle of the heart due to inadequate oxygen delivery to the myocardium with coronary artery disease being the most common cause. "Elevated serum levels of TNF were related to cachexia in patients with HF, while in ischemic cardiomyopathy, high TNF plasma concentrations were detected in patients with reduced LVEF." (PMID 39591456, 2024). "This study sought to assess the relationships between serum TNF-α levels, sTNFr1 and sTNFr2 and other biomarkers and some clinical parameters in patients with HFrEF due to non-ischemic cardiomyopathy, stratified according to their BMI." (PMID 36428528, 2022). "Even in rats with established ischemic cardiomyopathy, physical training was able to restore the Treg population and mitigate the production of IL-6, TNF-α, and later IL-17 in peripheral blood." (PMID 30203627, 2018). "Pentoxifylline administration to patients with ischemic cardiomyopathy inhibited pro-inflammatory cytokines and reduced apoptosis by decreasing TNF-α and Fas concentrations in plasma." (PMID 18269754, 2008). "Furthermore, TMZ treatment resulted in a significant decrease in serum TNF- α levels in ischemic cardiomyopathy patients." (PMID 39814796, 2025). "Thus, long-term activation of the NF-κB signaling pathway and the TNFα pathway suggests the persistence of systemic and local inflammatory responses, which play an important role in the deterioration of cardiac function in ischemic cardiomyopathy." (PMID 40114920, 2025). "Another study by the same group, involving 38 patients with ischemic cardiomyopathy, showed that PTX significantly improved LVEF and reduced inflammatory markers such as TNF-α and C-reactive protein (CRP)." (PMID 41066529, 2025). "Particularly, the levels of cytokines (e.g., IL-6, TNF-alpha) have been found higher in in patients with ischemic cardiomyopathy when compared with patients with non-ischemic cardiomyopathy." (PMID 35271674, 2022). "In patients with noninfectious ischemic cardiomyopathy, in comparison with placebo, PTX has previously shown cardioprotective effects in association with reductions in plasma concentrations of TNF." (PMID 27161638, 2016).
Japanese encephalitis (10 papers, 2012 to 2024). A disease due to a virus transmitted by an arthropod). "Following the analysis of the digestion patterns of four polymorphic sites of the TNF- alpha promoter region, a significant association was observed between the allele -308A and -863C with the patients of Japanese encephalitis." (PMID 22276993, 2012). "The present study aimed to associate the role of TNF-α promoter regions at positions -238, -308, -857 and -863 with disease progression and outcome in patients with Japanese encephalitis." (PMID 22276993, 2012). "In future, further elucidation of the immunoregulatory mechanism of TNF-α will be an important priority to enable the development of effective treatment strategies for Japanese encephalitis." (PMID 23940775, 2013). "Similarly, IFNs and proinflammatory cytokines including TNF-α and IL-6 were elevated in patients with acute Japanese encephalitis." (PMID 30016363, 2018). "TNF-α, IL-8, and IFN-α have been found to be related to poor outcomes in prior investigations of Japanese encephalitis (JE) patients." (PMID 36048783, 2022). "Microglial activation and release of inflammatory cytokines such as IL-6, IFN-γ and TNF-α can affect the differentiation and proliferation of neuroblasts in SVZ, as shown in a murine model of Japanese encephalitis." (PMID 28448579, 2017).
lower respiratory tract infection (10 papers, 2009 to 2024). "However, RA patients with concomitant BC, treated with biologic disease modifying drugs, such as anti TNFα, are at risk of lower respiratory tract infection, stressing the view that consequences of treatment of primary disease on the outcome of BC has to be carefully evaluated." (PMID 23094149, 2012). "MMPs stimulate proinflammatory cytokines, including TNFα, and exacerbate chronic lung infection and inflammation by promoting tissue damage and fibrosis." (PMID 39437760, 2024). "Another gene encoding a proinflammatory cytokine is tumor necrosis factor alpha (TNF-α), which has been associated with eosinophilic inflammation during lower respiratory tract infection with respiratory syncytial virus (RSV) in children." (PMID 21320344, 2011).
lymphedema (10 papers, 2009 to 2025). Excess fluid collection in tissues, causing swelling. "To determine the association of inflammatory cytokines with filarial lymphedema, we measured the plasma levels of IL-1β, IL-6, IL-12, and TNF-α in the four groups of subjects." (PMID 22685406, 2012). "Separate studies have corroborated these findings, noting correlation between IL-10, TNF-α, and TGFβ-1 levels and lymphedema-related factors following lymph node transfer." (PMID 38612716, 2024). "Recent studies have demonstrated that circulating levels of TNF-α, IL-10 and monocytes in lymphedema patients was significantly reduced following CDT when compared to control participants." (PMID 38612716, 2024). "Linear regression analysis revealed a significant positive correlation between TNF-α gene expression and tryptase-positive cells in the adipose tissue of lymphedema patients." (PMID 37886950, 2023). "In lymphedema, inflammatory fibrosis is first triggered at the cellular-molecular level via increased transcription of IL-6, IL-8, TNF-α, and TGF-β1." (PMID 36100619, 2022). "Molecular characterization of whole-tissue homogenates from mice with lymphedema revealed the prominence of inflammatory mediators such as tumor necrosis factor (TNF-α), underscoring the inflammatory nature of this acquired microvascular disorder." (PMID 20027220, 2009). "BmA induced significantly higher production of Th1-type cytokines—IFN-γ and TNF-α—in patients with lymphedema compared with asymptomatic individuals." (PMID 19381284, 2009). "TNF-α tissue levels were significantly higher in mice with NSAID-treated lymphedema (P<0.005) than in normal controls or mice with untreated or sTNF-R1-treated lymphedema." (PMID 20027220, 2009). "Our goals were to assess the therapeutic potential of systemic anti-inflammatory therapy and to examine the specific effects of TNF-α modulation in a model of acquired lymphedema." (PMID 20027220, 2009). "In addition to immune cell activation, lymphedema tissue has dramatically higher levels of pro-inflammatory cytokines TNF-α, IL-6, IL-8, and MCP-1, which can be used to measure the inflammatory response." (PMID 37886950, 2023). "In a mouse lymphedema model, the subcutaneous injection of ketoprofen decreased tail volume and suppressed histological changes such as epidermal thickening and neutrophil infiltration, while increasing the expression of tumor necrosis factor-α (TNF-α)." (PMID 35886961, 2022). "TNF-α may be required for tissue repair and that it appears to exert a permissive ameliorating effect in our model of acquired lymphedema." (PMID 20027220, 2009). "NSAID treatment significantly increased mRNA and protein levels of TNF-α while other inflammatory mediators such as MCP-3 and MIP1a were inhibited by NSAID treatment in lymphedema mice." (PMID 20027220, 2009). "Ketoprofen therapy reduces experimental post-surgical lymphedema, yet direct TNF-α inhibition does not." (PMID 20027220, 2009). "In overweight and obese patients with breast cancer-related lymphedema, a 10-week combination of low-calorie diet and synbiotic supplementation resulted in significant reductions in edema volume, serum leptin, and serum inflammatory marker levels (high-sensitivity CRP, IL-1β and TNF-α)." (PMID 35886961, 2022).
muscular dystrophy (10 papers, 2009 to 2025). Muscular dystrophy (MD) refers to a group of more than 30 genetic diseases characterized by progressive weakness and degeneration of the skeletal muscles that control movement. "In muscular dystrophy, chronic inflammation is driven by pro-inflammatory cytokines such as TNFα, IL1α, and IL1β." (PMID 34439837, 2021). "Thus, the analysis suggests a pro-inflammatory state in LGMDD2 patients also described for other muscular dystrophies, that is characterized by the alteration of IL-17 signaling pathway and the consequent increase of metallopeptidases activity and TNF response." (PMID 35646913, 2022). "In line with studies showing that the inhibition of the TNF signaling pathway is beneficial in DMD, our findings elucidate a new mode of action of TNF in downregulating Notch-1 that may be relevant in muscular dystrophies." (PMID 20814569, 2010).